SNORD42A (small nucleolar RNA, C/D box 42A)
Synonyms: U42; RNU42A; U42A
Gene: Small nucleolar RNA gene on chromosome 17 (28,723,429 to 28,723,492, forward strand). Ensembl gene ENSG00000238649.
Gene Ontology:
Biological process: RNA processing
Cellular component: nucleolus
Homologues: Orthologues: chimpanzee SNORD42 (100% identical), guinea pig SNORD42A (81% identical), macaque SNORD42 (81% identical), mouse Snord42a (80% identical), pig SNORD42 (80% identical), rabbit SNORD42 (80% identical), dog SNORD42 (78% identical), rabbit SNORD42 (78% identical), rat Snord42a (78% identical), tropical clawed frog SNORD42 (64% identical), tropical clawed frog SNORD42 (62% identical). Paralogues in human: SNORD42B (64% identical), SNORD42 (62% identical), SNORD42 (56% identical).
Diseases named in the same sentence as SNORD42A in open-access papers:
SNORD42A is named in the same sentence as 3 diseases in open-access papers, as found by Europe PMC text mining. Sharing a sentence is not in itself a finding about the gene and the disease. The quoted sentences say what the papers report.
acute myeloid leukemia (3 papers, 2022 to 2025). Acute myeloid leukemia (AML) is a group of neoplasms arising from precursor cells committed to the myeloid cell-line differentiation. "al. directly correlated SNORD42A KO with a loss of colony-forming capabilities and the slowing of cell proliferation and SNORD42A deletion with a reduction in cell size in acute myeloid leukemia (AML)." (PMID 38474168, 2024). "For example, SNORD42A promotes acute myeloid leukemia cell proliferation by directing 18S rRNA 2'-O-methylation that promotes protein translation." (PMID 36566215, 2022). "This suggests that SNORD42A-mediated rRNA modification modulates translation efficiency, thereby influencing the proliferation of acute myeloid leukemia cells, illustrating the mechanism by which SNHGs impact translation through snoRNA-mediated rRNA modification." (PMID 41301542, 2025).
autism (1 paper, 2025). Persistent deficits in social interaction and communication and interaction as well as a markedly restricted repertoire of activity and interest as well as repetitive patterns of behavior. "In addition, the expression level of certain snoRNAs was associated with the severity of autistic symptoms, with snoRA69 (also known as U69) being the most upregulated snoRNA and snoRD42A (U42) being the most downregulated snoRNA in children with severe autism." (PMID 40868063, 2025).
leukemia (1 paper, 2025). A malignant (clonal) hematologic disorder, involving hematopoietic stem cells and characterized by the presence of primitive or atypical myeloid or lymphoid cells in the bone marrow and the blood. "Consequently, leukemia cells lacking SNORD42A exhibit reduced cell size." (PMID 41301542, 2025).